PRNP (prion protein (Kanno blood group))
Diseases named in the same sentence as PRNP in open-access papers (continued):
Sharing a sentence is not in itself a finding about the gene and the disease.
infection (156 papers, 2006 to 2025). The state of being infected such as from the introduction of a foreign agent such as serum, vaccine, antigenic substance or organism. "Unlike other neurodegenerative disorders, in addition to idiopathic events or mutations to the PrP gene (PRNP), human prion diseases can also be acquired by infection (i.e., iatrogenic etiology)." (PMID 37156880, 2023). "Similar to the major amino acids of TSE-resistant animals mediating resistance to TSEs, PRNP gene polymorphisms are vulnerable to mediate TSE infections in sheep, goats, cattle, deer, and humans." (PMID 37808111, 2023). "Experimental infection of white-tailed deer expressing Q95/G96 (wt/wt), S96/wt, H95/wt or H95/S96 PrPC molecules confirmed the impact of PRNP polymorphisms on the incubation period." (PMID 36201049, 2023). "The probability of transfusion transmission at 10 months post-infection was associated with the donor PRNP codon 141 genotype, with the highest transmission rates for donors homozygous for leucine (141LL) at this position." (PMID 33600501, 2021). "A species barrier is absolute, for example, or a polymorphism of the PRNP is selected that conveys resistance against the infection, as is the case with kuru." (PMID 28670273, 2017). "Amino acid polymorphisms of the sheep PRNP gene have been linked to susceptibility and resistance to natural and experimental infection with TSEs." (PMID 26587837, 2015). "As observed in the New Zealand sheep, animals carrying the VRQ PRNP allele were fully susceptible to infection, with 100% attack rates, while ARQ/AHQ, ARQ/ARR, AHQ/ARR and ARR/ARR animals were resistant." (PMID 26587837, 2015). "Consistent with this possibility, fallow deer were reported to express a PRNP gene encoding 138 N and 226 E and resisted infection when housed together with CWD-infected mule deer for 7 years." (PMID 22723928, 2012). "However, due to the variation in survival periods associated with PRNP codon 141 genotype, 10 months post-infection actually represented between 15% and 61% of the total survival period for individual sheep." (PMID 33600501, 2021). "Several studies of natural and experimental scrapie infection in sheep and goats showed how allelic variations in the PRNP gene modulates disease susceptibility, and it is therefore critical to consider the PRNP gene sequence in wild ruminants for the assessment of TSE infection risk." (PMID 29631620, 2018). "However our results do provide information allowing comparison of the relative susceptibility of sheep of different PRNP genotypes to infection." (PMID 26587837, 2015). "The conversion of PrPC to PrPSc can occur via three different processes, including mutations of the PRNP gene that facilitate conversion of the normal to the diseased isoform, horizontal infection with biological materials containing PrPSc, or spontaneous conversion of unknown origin." (PMID 40149772, 2025). "This is significant as strains present at low levels within mixed infections could potentially become the dominant, disease-causing agent due to changes in the replication environment, for example sub-passage into a host with a different PRNP genotype." (PMID 34099797, 2021). "In cervids, there is also a close relationship between polymorphisms of the PRNP gene and CWD infection status." (PMID 34045540, 2021). "These CWD “hot zones” are particularly complex given the interplay between cervid PRNP genetics, the infection biology, the strain diversity of infectious prions and the long-term environmental persistence of infectivity, which hinder eradication efforts." (PMID 34488900, 2021). "In donor sheep, one animal of each PRNP genotype (141LL, 141FF, 141LF) tested positive at 4 months post-infection." (PMID 33600501, 2021). "The outcome of experimental challenges of sheep with TSE agents is governed to a greater or lesser extent by factors such as the agent strain type and titre, PRNP genotype, non-PRNP genes, route of infection, sheep breed and age eg." (PMID 26587837, 2015).
infection (continued). "One last point that remains to be addressed is the expression of the prion protein gene itself (PRNP in humans) upon infection." (PMID 24898206, 2014). "Two of these sheep (one from Group 1 and one from Group 3) had survival periods that were less than the shortest survival time of clinically positive sheep of the same PRNP genotype (141LF), and it is therefore possible that they were in the preclinical stages of infection." (PMID 35764688, 2022). "Blood was collected at 10 months post infection, which was estimated to be approximately halfway through the survival period based on previous experiments in which PRNP genotype ARQ/ARQ sheep were orally infected with similar doses of BSE-infected cattle brain homogenate (typically 20–24 months)." (PMID 33600501, 2021). "Cervid PRNP genetics have been widely studied in North America, where both natural and experimental infection of deer species has allowed for the identification of PRNP polymorphisms that are associated with reduced incidence of disease and/or slower disease progression." (PMID 31366372, 2019). "However, it is important to bear in mind the limitations associated with intracerebral inoculation, since the route of infection, together with PRNP genotype and prion strain is one of the key factors controlling the transmission barrier." (PMID 29975760, 2018). "When our New Zealand sheep heterozygous for the ARR PRNP allele were inoculated with SSBP/1, ARQ/ARR animals appeared to be totally resistant to infection, while in VRQ/ARR sheep it produced a 100% attack rate, with incubation periods that were not significantly different from VRQ/ARQ sheep." (PMID 26587837, 2015). "The unusually long observation period (6–8 years for most, but up to 12 years for others) allows us to draw robust conclusions about rates of survival of animals previously regarded as resistant to infection, particularly PRNP heterozygotes, and is the most comprehensive such study reported to date." (PMID 26587837, 2015). "In contrast, PRNP from reindeer 2 and 60 were heterozygous at bases 4 (codon 2, V/M), 385 (codon 129, G/S), 413 (codon 138, S/N), and 505 (codon 169, V/M) of PRNP (cervid numbering), and completely resisted infection with CWDELK up to 60 mpi." (PMID 22723928, 2012). "It should be stressed that resistance in the context presented in the present study does not mean absolute immunity to infection; instead, it implies a measurably lower risk of infection and an altered disease course in animals with rare PRNP variants found to be infected." (PMID 34573378, 2021). "An important role for PRNP polymorphisms in determining disease susceptibility is also suggested by the finding that one of the three reindeer has not yet succumbed to infection with the CWDWTD inoculum by 26 mpi and showed no detectable PrPCWD in lymphoid tissue at 25 mpi." (PMID 22723928, 2012). "Positive and negative CWD infection status were correlated to PRNP genotypes using the 96GG genotype as a reference point to assess odds ratios of infection." (PMID 31790424, 2019). "In our infection test, the control cells, non-transduced and empty vector transfected only, did not propagate prion infection, whereas the bovine PRNP transduced cell lines were able to be infected." (PMID 25647616, 2015). "Also, the expression of PRNP varied with MDV infection and infection time." (PMID 38183097, 2024). "In the present study, we evaluate both infection status and disease stage in nearly 2100 farmed deer depopulated in the United States and Canada, including 714 CWD-positive deer and correlate our findings with PRNP genotype, including the more rare 95H, 116G, and 226K alleles." (PMID 31790424, 2019).
neurodegenerative disease (126 papers, 2006 to 2026). A disorder of the central nervous system characterized by gradual and progressive loss of neural tissue and neurologic function. "Interestingly, an increasing number of PRNP mutations have been recently linked to neurodegenerative diseases other than CJD, including FTD-like, AD-like clinical pictures or other unique clinical phenotypes." (PMID 30606247, 2019). "We identified 70 additional novel and missense variants in other genes, such as MAPT, GRN, CSF1R, and PRNP, related to neurodegenerative diseases, which may represent overlapping clinical and neuropathological features with AD." (PMID 31182772, 2019). "Further screening of PRNP 1368 polymorphism and other neurodegenerative diseases associated genes, such as ApoE4 allele frequency, in Chinese sCJD patients may help to understand their potential contributions to the occurrence of sCJD." (PMID 23671608, 2013). "Therefore, we suggest that the polymorphism of PRNP 1368, located in the promoter region, may influence the expression of the PRNP gene; the promoter polymorphisms of PRNP might also be associated with other neurodegenerative diseases." (PMID 19351416, 2009). "Instead, NDR1/2 KO brains had significant increases in proteins associated with human neurodegenerative diseases (e.g., ApoE, Htt, APP, and PRNP), highlighting similarities between this mouse model and human disorders." (PMID 36446521, 2023). "In the sections that follow, we highlight associations of several genes (e.g., MAPT, PRNP, GRN) with clinical EOAD that are better known for their role in other neurodegenerative diseases." (PMID 35393555, 2022). "No additional pathogenic mutations were found in other dominant causative genes of AD, FTD, or of other neurodegenerative diseases, such as APP, PSEN2, PRNP, PGRN, or MAPT." (PMID 30917570, 2019). "Thus, according to these four studies, the introduction of a single (or two) amino acidic change(s) in PRNP in a critical position can cause remarkably different neurodegenerative diseases and may be sufficient to create distinct protein-based infectious prions." (PMID 24454379, 2013). "Intriguingly, specific pathogenic variants in PRNP and MAPT—genes which are more commonly associated with other neurodegenerative diseases—may provide unexpectedly important insights into the formation of AD tau pathology." (PMID 35393555, 2022). "Overall, the evidence presented here based on miRNA profiles strongly implicates the prion pathway in other neurodegenerative diseases, and potentially without mutations to the PRNP gene." (PMID 31037649, 2019). "Along with V180I mutations in PRNP, genetic variations in other genes, such as lipoprotein(a) (LPA), Leucine-rich repeat kinase 2 (LRRK2), and fibroblast growth factor 20 (FGF20), which are directly or indirectly related to neurodegenerative diseases, were also observed in patients with V180I gCJD." (PMID 31238786, 2019). "The polymorphism M129V of the PRNP gene was confirmed as a nonspecific genetic risk factor for all transmissible spongioform encephalopathies, (influencing the susceptibility to CJD and the outcome of the disease) and also for other neurodegenerative diseases." (PMID 33917419, 2021).
cancer (65 papers, 2013 to 2025). A tumor composed of atypical neoplastic, often pleomorphic cells that invade other tissues. "We aimed to explore the potential of PRNP serving as a therapeutic target for immunotherapy in cancer by investigating its association with tumor immunity." (PMID 39170916, 2024). "Among most cancer types, PRNP is expressed at high levels, which is linked to the prognosis of patients." (PMID 39170916, 2024). "We aimed to explore the associations between PRNP and 60 common immune checkpoint expressions (24 inhibitory and 36 stimulatory) across various cancers." (PMID 39170916, 2024). "Kyoto Encyclopedia of Genes and Genomes (KEGG) pathway analysis indicated that PRNP was potentially linked with several cancer-associated signaling pathways, including regulation of inflammatory response and oxidative phosphorylation." (PMID 37535656, 2023). "Prions are often overexpressed in many forms of cancer, and the prion protein gene (PRNP) was detected by means of in silico analysis to be mutated in some cancer patients." (PMID 35163973, 2022). "We also analyzed somatic mutations of the PRNP gene in cancer patients by PolyPhen-2, PANTHER, and PROVEAN." (PMID 32560489, 2020). "In the present study, we identified a total of 48 somatic mutations in the PRNP gene in 10,967 cancer patients." (PMID 32560489, 2020). "To find somatic mutations in the PRNP gene in cancer tissues, we searched the information on somatic mutations in the PRNP gene in cancer patients using the Cancer Genome Atlas (TCGA) database." (PMID 32560489, 2020). "Further validation of distant metastatic property in cancer cells carrying PRNP mutations is highly desirable in the future." (PMID 32560489, 2020). "To identify somatic mutations in the PRNP gene in cancer tissues, we analyzed somatic mutations in the PRNP gene in cancer patients using the Cancer Genome Atlas (TCGA) database." (PMID 32560489, 2020). "We identified significantly different distributions among the types of cancer, the mutation counts, and the ages of diagnosis between the total cancer patient population and cancer patients carrying somatic mutations in the PRNP gene." (PMID 32560489, 2020). "Using cBioPortal, we identified a total of 48 somatic mutations in the PRNP gene in 10,953 cancer patients." (PMID 32560489, 2020). "Notably, we observed a significant association between PRNP(PrPC) and the majority of immune checkpoint molecules across various cancer types, particularly robust correlations with CD274 and C10orf54." (PMID 39170916, 2024). "On the basis of these studies, we postulated that cancer patients carrying pathogenic somatic mutation of the PRNP gene may produce a basal level of PrPSc in peripheral tissues and may not be diagnosed with prion disease." (PMID 32560489, 2020). "In addition, we predicted the amyloid propensity of the somatic mutations in the PRNP gene in cancer patients." (PMID 32560489, 2020). "Notably, four somatic mutations—L125F, E146Q, R151C, and K204N—were newly identified amyloid-prone somatic mutations in the PRNP gene in cancer patients." (PMID 32560489, 2020). "In addition, we compared the information on cancer patients who carried somatic mutations of the PRNP gene with that of the total cancer patient population." (PMID 32560489, 2020). "Since PrP protects cancer cells against apoptotic stress and contributes to tumorigenesis, the difference on distribution of somatic mutation of the PRNP gene may be induced depending on the degree of contribution of PrP to different cancer types." (PMID 32560489, 2020). "In addition, we compared the information on the somatic mutations in the PRNP gene in cancer patients with that of previously reported pathogenic mutations associated with prion diseases and with the total cancer patient population." (PMID 32560489, 2020). "In conclusion, we identified 48 somatic mutations in the PRNP gene in 10,967 cancer patients." (PMID 32560489, 2020).
cancer (continued). "Moreover, as reported here, the association between PRNP and vesicular dynamics has a potential impact in the biology of several types of solid tumors, strengthening this pathway as putative novel target for cancer therapeutic strategies." (PMID 38347462, 2024). "Additionally, we also found that PRNP protein expression was associated with cancer stages of OC." (PMID 36213323, 2022). "Thus, we postulated that cancer tissue may induce somatic mutations in the PRNP gene, which can trigger the onset of prion diseases." (PMID 32560489, 2020). "Thus, the somatic mutations in the PRNP gene in cancer tissues are very important." (PMID 32560489, 2020). "In addition, to evaluate whether the somatic mutations in the PRNP gene in cancer patients had a damaging effect, we performed in silico analysis using PolyPhen-2, PANTHER, PROVEAN, and AMYCO." (PMID 32560489, 2020). "Furthermore, to assess whether the somatic mutations in the PRNP gene in cancer patients are deleterious, we performed in silico annotation using PolyPhen-2, PANTHER, PROVEAN, and AMYCO." (PMID 32560489, 2020). "Thus, we postulated that genetically unstable cancer tissue may cause somatic mutations in the prion protein gene (PRNP), which could trigger the onset of prion diseases." (PMID 32560489, 2020). "Given the pivotal role of PrPc in tumor progression, targeting its suppression emerges as a promising therapeutic strategy for cancer treatment, though research on the post-transcriptional regulation of PRNP remains limited." (PMID 39972491, 2025). "Our findings revealed that PRNP is significantly upregulated in most cancers, with only a few exceptions." (PMID 39170916, 2024). "Strong associations were observed between the expression level of PRNP and MSI as well as TMB across distinct cancer types." (PMID 39170916, 2024). "Further exploration is required to obtain an integrated view of the complex regulation of the PRNP gene in cancer." (PMID 38589873, 2024). "To evaluate if our findings extended to other cancers, we analyzed the impact of PRNP expression in other tumor types." (PMID 38347462, 2024). "To elucidate the implications of PRNP/PrPC in the biology of this cancer, we analyzed publicly available RNA sequencing (RNA-seq) data of patient-derived GBMs from four independent studies." (PMID 38347462, 2024). "Then, we visualized how PRNP expression was distributed across the tumors, finding that PRNP is widely expressed in cancer cells, and its levels are heterogeneous among different samples." (PMID 38347462, 2024). "We used various publicly available databases to assess the expression of PRNP(PrPC) and the prognostic implications it poses on various cancer types." (PMID 39170916, 2024). "The role and function of PRNP(PrPC) in influencing the proliferation, apoptosis, invasion, and metastasis of different cancer types indicate its potential as a promising therapeutic target involved in the therapeutic management of cancer." (PMID 39170916, 2024). "The expression of PRNP mRNA in 33 kinds of cancer and their adjacent normal tissues was compared via GEPIA." (PMID 38370370, 2024). "Comprehensive analyses were conducted on The Cancer Genome Atlas (TCGA) Pan-Cancer dataset from the University of California Santa Cruz (UCSC) database to determine the expression of PRNP and its potential prognostic implications." (PMID 39170916, 2024). "Our results showed that, for most cancer types, PRNP displayed significantly positive correlations with several vesicle dynamics signatures in at least one tumor stage." (PMID 38347462, 2024). "Our investigation of PRNP(PrPC) expression in pan-cancer revealed significant upregulation in various cancer types, such as BRCA, COADREAD, ESCA, and STAD." (PMID 39170916, 2024). "The theory is founded on the observation that PRNP(PrPC) can promote anti-apoptosis, invasion, proliferation, and metastasis of cancer cells via different signal transduction pathways and a series of cascading reactions." (PMID 39170916, 2024).